ZBTB41 (zinc finger and BTB domain containing 41)
Description:
May be involved in transcriptional regulation.
Synonyms: FRBZ1; FLJ36199; DKFZp686C06120; ZNF924
Tractability: PROTAC: ubiquitination databases record sites on it; its protein half-life has been measured.
Gene: Protein-coding gene on chromosome 1 (197,153,682 to 197,201,449, reverse strand). Ensembl gene ENSG00000177888.
Subcellular location: Nucleus
Subcellular location (Human Protein Atlas): Nuclear membrane; Cytosol; Nucleoplasm
Gene Ontology:
Molecular function: DNA-binding transcription factor activity, RNA polymerase II-specific; RNA polymerase II cis-regulatory region sequence-specific DNA binding
Biological process: regulation of transcription by RNA polymerase II
Cellular component: nucleus
Genetic constraint (gnomAD): Loss-of-function variants: 30 observed, 70.49 expected, observed/expected ratio (o/e) 0.43, 90% interval 0.32 to 0.58. The upper end of that interval is the gene's LOEUF score, 0.58, which puts it in group 2 of 6, group 1 being the genes least tolerant of losing a copy. Missense variants: 731 observed, 1,023.6 expected, observed/expected ratio (o/e) 0.71, 90% interval 0.67 to 0.76. Synonymous variants: 345 observed, 352.91 expected, observed/expected ratio (o/e) 0.98, 90% interval 0.89 to 1.07.
Homologues: Orthologues: chimpanzee ZBTB41 (100% identical), macaque ZBTB41 (99% identical), rabbit ZBTB41 (97% identical), dog ZBTB41 (97% identical), guinea pig ZBTB41 (97% identical), pig ZBTB41 (95% identical), rat Zbtb41 (94% identical), mouse Zbtb41 (94% identical), tropical clawed frog zbtb41 (62% identical), zebrafish zbtb41 (57% identical). Paralogues in human: ZNF407 (15% identical), ZNF644 (15% identical), ZBTB17 (13% identical), ZNF527 (13% identical), ZNF287 (12% identical), ZNF333 (12% identical), ZKSCAN7 (12% identical), ZNF214 (12% identical), ZNF17 (11% identical), ZNF572 (11% identical), ZNF774 (11% identical), ZNF697 (11% identical), and 38 more.
Diseases named in the same sentence as ZBTB41 in open-access papers:
ZBTB41 is named in the same sentence as 4 diseases in open-access papers, as found by Europe PMC text mining. Sharing a sentence is not in itself a finding about the gene and the disease. The quoted sentences say what the papers report.
cervical cancer (1 paper, 2021). A primary or metastatic malignant neoplasm involving the cervix. "Furthermore, clone formation assays in the HeLa cell line (cervical cancer cell line) revealed that TAF1A and ZBTB41 knockdown significantly inhibits cell proliferation." (PMID 33311601, 2021).
hepatocellular carcinoma (1 paper, 2021). A malignant tumor that arises from hepatocytes. "In hepatocellular carcinoma, ZBTB41 has been found to be a hub gene that was upregulated and regulated of the expressions of several key miRNAs." (PMID 33311601, 2021).
cancer (1 paper, 2021). A tumor composed of atypical neoplastic, often pleomorphic cells that invade other tissues. "Besides, ROC curve analysis showed a modest but useful contribution of the TAF1A and ZBTB41 genes to the diagnostic efficiency of the high and low pathological grades of cancer (grade III/IV vs. grade I/II)." (PMID 33311601, 2021).
tumour (1 paper, 2021). "More convincingly, the qRT-PCR clinical tissue samples showed a significant upregulation of TAF1A (P < 0.01) and ZBTB41 (P < 0.05) in tumours compared to the normal healthy tissues." (PMID 33311601, 2021). "Subsequent experiments showed that the TAF1A and ZBTB41 gene expression in the tumour and normal tissues were significantly different." (PMID 33311601, 2021). "In this study, cytological experiments revealed that the TAF1A and ZBTB41 might be involved in the proliferation and migration of tumour cells, and that they may interact endogenously." (PMID 33311601, 2021). "Furthermore, the TAF1A and ZBTB41 were significantly overexpressed in 304 high-grade tumour samples retrieved from the TCGA database (*P < 0.05, **P < 0.01)." (PMID 33311601, 2021). "Additionally, the wound scratch healing assay showed that TAF1A and ZBTB41 knockdown inhibits tumour cell migration." (PMID 33311601, 2021).